NRF1 (nuclear respiratory factor 1)
Description:
Transcription factor that activates the expression of the EIF2S1 (EIF2-alpha) gene. Links the transcriptional modulation of key metabolic genes to cellular growth and development. Implicated in the control of nuclear genes required for respiration, heme biosynthesis, and mitochondrial DNA transcription and replication.
Synonyms: Alpha-pal; EWG
Tractability: PROTAC: UniProt records ubiquitination sites on it; ubiquitination databases record sites on it; its protein half-life has been measured.
Gene: Protein-coding gene on chromosome 7 (129,611,699 to 129,757,082, forward strand). Ensembl gene ENSG00000106459.
Subcellular location: Nucleus
Subcellular location (Human Protein Atlas): Nucleoplasm; Cytosol
Pathways (Reactome):
Cellular responses to stimuli: Mitochondrial unfolded protein response (UPRmt)
Metabolism: PPARA activates gene expression
Organelle biogenesis and maintenance: Transcriptional activation of mitochondrial biogenesis
Gene Ontology:
Molecular function: DNA-binding transcription activator activity, RNA polymerase II-specific; protein binding; RNA polymerase II cis-regulatory region sequence-specific DNA binding; DNA-binding transcription factor activity, RNA polymerase II-specific; protein homodimerization activity; DNA-binding transcription factor activity
Biological process: positive regulation of transcription by RNA polymerase II; regulation of transcription by RNA polymerase II
Cellular component: extracellular exosome; nucleoplasm; nucleus
Genetic constraint (gnomAD): Loss-of-function variants: 4 observed, 48.65 expected, observed/expected ratio (o/e) 0.0822, 90% interval 0.04 to 0.19. The upper end of that interval is the gene's LOEUF score, 0.19, which puts it in group 1 of 6, group 1 being the genes least tolerant of losing a copy. Missense variants: 257 observed, 596.44 expected, observed/expected ratio (o/e) 0.43, 90% interval 0.39 to 0.48. Synonymous variants: 204 observed, 230.15 expected, observed/expected ratio (o/e) 0.89, 90% interval 0.79 to 1.
Homologues: Orthologues: chimpanzee NRF1 (100% identical), rabbit NRF1 (99% identical), dog NRF1 (99% identical), pig NRF1 (99% identical), tropical clawed frog nrf1 (93% identical), zebrafish nrf1 (92% identical), macaque NRF1 (91% identical), guinea pig NRF1 (91% identical), mouse Nrf1 (90% identical), rat Nrf1 (90% identical), Drosophila melanogaster ewg (45% identical), Drosophila melanogaster ova (16% identical).
Diseases named in the same sentence as NRF1 in open-access papers:
NRF1 is named in the same sentence as 194 diseases in open-access papers, as found by Europe PMC text mining. Sharing a sentence is not in itself a finding about the gene and the disease. The quoted sentences say what the papers report.
breast carcinoma (49 papers, 2008 to 2025). "Specifically, we report a novel oncogenic function of NRF1 supporting its causative role in breast cancer development and progression." (PMID 30486409, 2018). "NRF1 activity is significantly associated with breast cancer and patient survival." (PMID 39614126, 2025). "In summary, this study suggests that the herbal recipe SLC has the potential to act as an agent for inhibiting OXPHOS through the PDK1/PDHA1 and SIRT1/PGC-1α/NRF1/TFAM signaling axis to treat HER2-positive breast cancer." (PMID 41465397, 2025). "The nuclear respiratory factor 1 (NRF1) transcription factor has been shown to exhibit high activity in various human tumors, with aberrant expression contributing to the acquisition of breast cancer stem cell (BCSC) properties." (PMID 40709187, 2025). "We also confirmed via qRT-PCR that proteasome subunit genes, such as PSMB7 and PSMD12, which are induced by NRF1 when the proteasome is inhibited, had attenuated expression in the NRF1-knockdown breast cancer cell lines." (PMID 37739987, 2023). "It acts as a master regulator of mitochondrial biogenesis via NRF transcription factors (NRF1 and NRF2, NRF1 is up regulated in breast cancer metastases and in metastases by various cancers to liver, peritoneum, and adrenals)." (PMID 38039408, 2023). "Taken together, our results point to TNBC as a particularly vulnerable breast cancer subtype to proteasome inhibition and provide a proof-of-principle for targeting NRF1 as a viable means to increase the efficacy of proteasome inhibitors in TNBC tumors." (PMID 37739987, 2023). "Combined with chip-seq data acquired from Cistrome Data Browser and molecular experiments, we proved that NRF1 is the accurate TF for PTPN2 in breast cancer cell lines." (PMID 36341348, 2022). "First, we performed a Western blot of NRF‐1 on mammary tumors derived from the young and aged mice and found that NRF‐1 is significantly up‐regulated in the aged mice." (PMID 36111352, 2022). "Supporting this interpretation, a significant correlation between OGT, an NRF1 activator, and proteasome subunit genes was observed in clinical breast cancer specimens." (PMID 33535386, 2021). "Intriguingly, datasets deposited in The Cancer Genome Atlas (TCGA) revealed a positive correlation between proteasome subunit expression levels and OGT levels, which is regarded as an NRF1 activator, in breast cancer cases." (PMID 33535386, 2021). "Next, we performed digital footprinting analysis and detected footprints for E2F and Nuclear Respiratory Factor 1 (NRF1), key transcription factors associated with breast cancer progression and response to therapies." (PMID 30679562, 2019). "We have previously reported the role of NRF1 in transcriptional programming of mitochondrial biogenesis in estrogen-induced growth of breast cancer cells." (PMID 30486409, 2018). "To test the impact of NRF1 signaling in the pathogenesis of estrogen-induced breast cancer, it is critical that we validate our in vitro observations by in vivo studies." (PMID 30486409, 2018). "In summary, multiple lineages of human breast cancer stem/progenitor cells were identified by profiling with stem cell markers in NRF1- and/or E2-treated normal MCF10A cells." (PMID 30486409, 2018). "ER+PR+HER+ breast cancer specimens had the highest levels of NRF1, followed by other subtypes of breast cancer (box plot in the bottom panel)." (PMID 30486409, 2018). "To understand the mechanistic aspects of the contribution of NRF1 in susceptibility to the breast carcinogenicity, we focused our efforts on NRF1 motif enriched CXCR4 gene, which is implicated in breast cancer." (PMID 30486409, 2018). "We postulated that NRF1 re-programming contributes to the acquisition of breast tumor initiating stem (BTIS) cells (breast cancer stem cells) via EMT." (PMID 30486409, 2018).
breast carcinoma (continued). "We have previously shown nuclear respiratory factor 1 (NRF1)-mediated transcriptional programming of mitobiogenesis contributes to estrogen-induced breast cancer through modulating cell cycle progression." (PMID 30486409, 2018). "The gain of NRF1 and/or treatment with 17β-estradiol (E2) produced heterogeneous breast cancer stem cell (BCSC)-like subsets composed of more than 10 distinct cell sub-populations." (PMID 30486409, 2018). "Consistent with our observation of NRF1-driven breast tumorigenesis in the experimental model, higher protein levels of NRF1 were also found in human breast cancer tissue specimens." (PMID 30486409, 2018). "The NRF1 BCSC-like subset showed resistance to these agents just as observed for breast-cancer-resistant MDA-MB231 cells." (PMID 30486409, 2018). "The contribution of CXCR4 to reprogramming breast cancer cells to cancer stem cells is of particular interest to our research on NRF1." (PMID 30486409, 2018). "Our finding is consistent with a recent report showing increased levels of NRF1 protein in breast cancer patients who underwent surgery at the Changhai Hospital of Shanghai, China." (PMID 30486409, 2018). "In summary, a gain in NRF1 expression and/or treatment with E2 led to reprogramming of normal breast epithelial cells to acquire the breast cancer stem cell signature CD24−/CD44+." (PMID 30486409, 2018). "Our findings were validated by a recent study using TGCI normal and breast tumor specimens in which it was shown that NRF1 activity was significantly higher in human breast cancers compared to adjacent surrounding control breast tissue." (PMID 30486409, 2018). "Our finding showed that NRF1 levels were significantly higher in all four subtypes of breast cancers (ER+PR+HER+, ER+PR+HER−, ER−PR−HER+, and ER−PR−HER−) compared with control tissue (p < 0.001)." (PMID 30486409, 2018). "The activation of NRF1 was studied in the context of the upregulation of the CXCR4 gene involved in the development of E2-dependent breast cancer." (PMID 30486409, 2018). "In breast cancer cells with acquired resistance to tamoxifen, the ER-a network (of which NRF1 is a component) lost responsiveness to 17-beta-estradiol; this loss of responsiveness was mediated by epigenomic changes." (PMID 28589855, 2017). "NRF-1 expression is selectively upregulated in human breast cancer cells relative to adjacent stromal tissue, which correlates with metastasis and poor prognosis." (PMID 28993637, 2017). "Little is known about the role of NRF-1 in the pathogenesis of cancer except that it promotes survival and proliferation of breast cancer cells." (PMID 29050218, 2017). "Surprisingly, mitochondrial content or number was reduced despite elevated regulators that promote mitochondrial biogenesis (i.e., PGC1α, NRF1, and Tfam) in breast cancer cells." (PMID 27746856, 2016). "Here, we show that upregulation of mitochondrial fission protein, dynamin related protein-1 (Drp1), was accompanied with increased mitochondrial biogenesis markers (PGC1α, NRF1, and Tfam) in breast cancer cells." (PMID 27746856, 2016). "Consistent with our current findings, we have previously shown that a PGC1/NRF1 gene signature predicts tumor recurrence, metastasis and poor overall survival in ER(+)/Luminal-A breast cancer patients." (PMID 26087310, 2015). "This PGC1/NRF1 gene signature was also elevated in >2,000 human tumors excised from breast cancer patients, including both ER(+) and ER(−) cases." (PMID 26087310, 2015). "Knockdown of NRF-1 in MCF-7 breast cancer cells using siRNA increases apoptosis and overexpression of NRF-1 inhibits 4-OHT-mediated apoptosis." (PMID 24534923, 2014). "Investigation of low BRCA1 expression in the human breast cancer cell line SK-BR-3 revealed a transcriptional network consisting of NRF-1 > GABPβ > BRCA1." (PMID 21609478, 2011).
breast carcinoma (continued). "The pattern of expression in rho0 cells and among breast cancer cell lines was similar in that the genes encoding the COX protein complex, as well as the COX master regulator NRF1, were down-regulated." (PMID 21935467, 2011). "Using this method, we demonstrated that cis-regulatory motifs bound by ELK1, E2F, NRF1 and NFY are most significantly associated with breast cancer malignancy." (PMID 18823535, 2008). "Our analysis identified cis-regulatory motifs bound by ELK1, E2F1, NRF1 and NFY as principal motifs associated with breast cancer malignancy." (PMID 18823535, 2008). "Although we focused on a proteasome-sensitive TNBC model in our current work, it is possible that this general strategy of targeting the NRF1-proteasome axis could be successful in other breast cancer subtypes or even in other types of solid tumors." (PMID 37739987, 2023). "In addition, the high expression of NRF-1 is closely correlated with poor survival in the luminal A (ER+/PR+/HER2−) subtype of breast cancer." (PMID 30970566, 2019). "Furthermore, we have also shown that reactive oxygen species (ROS)-mediated activation of NRF1 is critical for the growth of estrogen-induced breast cancer cells and estrogen-induced malignant breast cell transformation." (PMID 30486409, 2018). "In summary, the major novel findings of this study illustrate new roles of NRF1 in helping to acquire breast tumor initiating stem-like cells and in regulating EMT and invasiveness of BCSCs, thus opening a new direction of NRF1’s role in breast cancer research." (PMID 30486409, 2018). "We have recently shown that activation of the NRF1 pathway may participate in the development of breast tumors; however, its contribution to the acquisition of cancer stem cells remains unexplored in breast cancer." (PMID 30486409, 2018). "Therefore, we also examined NRF1 protein expression in tissue samples from the breast cancer subtypes stratified based on the status of ER, PR, and Her2 receptor status." (PMID 30486409, 2018). "Stochastic heterogeneous BCSCs generation may provide a better understanding of how E2-dependent breast neoplasms depend on the NRF1 network, and this may open new avenues for therapies against breast cancer." (PMID 30486409, 2018). "The actual role NRF1 plays in breast cancer remains the least studied of all transcription factors." (PMID 30486409, 2018). "Further clinical validation of this finding may lead to new avenues for NRF1 targeted therapeutic strategies to fight breast cancer." (PMID 30486409, 2018). "We have shown that estrogen-induced malignant breast tumor formation is NRF1-dependent." (PMID 30486409, 2018). "Importantly, an in silico approach has already nominated PGCs and NRF1 as key proteins regulating bioenergetics in breast cancer cells." (PMID 26919657, 2016). "Furthermore, we used the clinical resources in the starBase database and the Student's t-test and Pearson's correlation to analyze the expression levels and detect correlations between miR-504 and NRF1 in 748 breast cancer samples." (PMID 26201446, 2015). "In human breast cancer cells, on the other hand, estradiol produces high rates of mitochondrial reactive oxygen species (ROS) that act as signal transducing factors activating NRF-1." (PMID 22676897, 2012). "ER + breast cancer patient RNAseq data from TCGA revealed an association of ROS and PPAR signaling with NNAT expression and in silico analysis of the NNAT promotor revealed consensus binding sites for NRF1 and PPARα/PPARγ, as well as the cell cycle transcription factor, E2F4." (PMID 37400769, 2023). "Whether NRF1 contributes to estrogen carcinogenesis in breast cancer is not fully understood." (PMID 30486409, 2018). "Our discovery of targeting transcriptional activation of CXCR4 to inhibit NRF1-induced oncogenic transformation provides a mechanistic explanation for estrogen-dependent breast carcinogenesis and opens new avenues in strategic therapeutics to fight breast cancer." (PMID 30486409, 2018).
breast carcinoma (continued). "The purpose of this study was to investigate whether NRF1-modulated CXCR4 expression drives estrogen-induced malignant transformation of breast epithelial cells to BCSCs and whether this NRF1 activity plays a major role in breast cancer development and progression." (PMID 30486409, 2018). "Overall, SLC influences oxidative phosphorylation via the PDK1/PDHA1 and SIRT1/PGC-1α/NRF1/TFAM signaling pathways and downregulates the HER2 pathway, thereby ultimately inhibiting HER2-positive breast cancer progression." (PMID 41465397, 2025). "These include EMT (TWIST1, SNAIL1, RUNX1, RUNX2, HIF1, and NOTCH1), breast cancer maintenance (OCT4, SP1, GATA1, ATF1, FOXO3a, ELK1, VDR, and NRF1), pro-metastatic responses (SMAD2/3, HNF1a, GLI1, NANOG, YY1, MYB1, and AP1), and immune modulation (STAT1/3)." (PMID 38398186, 2024). "Briefly, the ER + breast cancer cell lines, T47D and ZR75, were co-transfected with the NNAT promoter-reporter construct, and plasmids that constitutively expressed E2F1, E2F4, NRF1, PPARα/RXR, PPARγ/RXR, or control (pLX304)." (PMID 37400769, 2023). "Nuclear respiratory factor 1 (NRF1) is a transcription factor regulating important metabolic genes involved in cell growth and is found to behave similar to an oncoprotein in breast cancer." (PMID 35681777, 2022). "Nonetheless, similar observations were made in breast cancer cells were the interaction between PHD1 and NRF1/PGC1α to preserve mitochondrial function during tumor growth was enhanced during hypoxia and was also independent of PHD1’s hydroxylation activity." (PMID 31924757, 2020). "In breast cancer cells, LCA induces mitochondrial biogenesis through NRF1, AMPK, and PGC-1β; the same effectors are also induced in murine breast cancer models upon LCA feeding." (PMID 30934972, 2019). "An ABCB1 fusion involving NRF1 was found in Patient 14 that co-occurred with an SLC25A40–ABCB1 fusion, demonstrating that convergent ABCB1 deregulation also occurs in breast cancer patients." (PMID 30894541, 2019). "Next, we checked the expression level of NRF1 and SIAH2 in clinical samples and found that NRF1 and SIAH2 were abundant in normal and breast cancer tissues, respectively." (PMID 30833558, 2019). "The combined NRF1 overexpression and treatment with E2 also led to reprogramming of CD24+ and CD24−CD44− subpopulations with multiple breast cancer stem cell signatures containing ALDH1A1, EpCAM, CXCR4, or CD133." (PMID 30486409, 2018). "Recently we have shown that NRF1 expression was increased in MCF10A cells upon E2 exposure and that estrogen-induced breast cancer cell growth was reduced by the inhibition of NRF1 expression." (PMID 30486409, 2018). "Assessment of the expression of other BCSC markers -ALDH1A1, EpCAM, CXCR4, and CD133 in stable NRF1 overexpressing CD44+CD24− and CD44+CD24+ subpopulations showed as many as 10 different downstream breast cancer progenitor cell subpopulations." (PMID 30486409, 2018). "Motifs bound by ELK1, E2F, NRF1, and NFY positively correlate with malignant progression of breast cancer." (PMID 30486409, 2018). "Estrogen treatment increases mitochondrial mass, the DNA-binding activity of NRF1, a regulator of TFAM, and the level of TFAM, and TFAM shRNA inhibits colony formation in E2-treated breast cancer cells." (PMID 30486409, 2018). "The mechanism by which NRF1 drives the expression of embryonic pluripotency transcription factors, OCT4, SOX2, and NANOG necessary for maintaining breast cancer cell stemness remains to be determined." (PMID 30486409, 2018). "Our analysis found that motifs bound by ELK1, E2F, NRF1 and NFY are potential regulatory motifs that positively correlate with malignant progression of breast cancer." (PMID 18823535, 2008).